FUS (FUS RNA binding protein)
Diseases named in the same sentence as FUS in open-access papers (continued):
Sharing a sentence is not in itself a finding about the gene and the disease.
osteosarcoma (5 papers, 2020 to 2021). A usually aggressive malignant bone-forming mesenchymal neoplasm, predominantly affecting adolescents and young adults. "To discern roles of FUS in genome protection, we disrupted FUS gene loci in U-2 OS osteosarcoma cells using CRISPR–CAS9 followed by genetic reconstitution with a retroviral vector encoding the untagged FUS ORF (see Experimental procedures section)." (PMID 34375640, 2021). "Moreover, wildtype FUS and TDP43 proteins have been found to localize to sites of DNA damage in human osteosarcoma epithelial cells and appear to function in the prevention of transcription-coupled DNA damage and in repair of DNA repair." (PMID 32005289, 2020).
retinal degeneration (5 papers, 2015 to 2024). Degeneration of the retina. "The FUS-P525L mutation exacerbates FUS-induced retinal degeneration by increasing the FUS cytoplasmic distribution." (PMID 38500677, 2024). "Flies expressing K510Q mutant FUS in photoreceptors exhibited retinal degeneration, with reduced pigmentation and a loss of ommatidia." (PMID 31866807, 2019). "However, in contrast to the TDP-43 mutation case, LonP1 overexpression in the FUS-ALS D. melanogaster model exacerbated retinal degeneration, with increased neurodegeneration, while silencing mtUPR-related genes ameliorated mutant FUS-induced neurodegeneration." (PMID 38136659, 2023). "Down-regulating expression of HSP60A, HSP60B orHSP60C in photoreceptors suppressed the FUS-induced retinal degeneration phenotype to various extents, with siHSP60B showing the most robust effect, although knocking-down HSP60 did not affect the expression level of FUS." (PMID 26335776, 2015). "Thus, we cannot rule out the possibility that the reduction of FUS protein caused by phosphorylation by as yet unknown mechanism(s) that took place in the Drosophila retinal photoreceptor neurons might have partly contributed to the amelioration of retinal degeneration induced by FUS." (PMID 35753345, 2022).
soft tissue tumors (5 papers, 2020 to 2023). "EWSR1/FUS::NFATC2 rearrangements are promiscuous gene fusions found in both benign and malignant bone and soft tissue tumors." (PMID 36555836, 2022).
thyroid cancer (5 papers, 2017 to 2022). "In summary, we conclude that SLC8A1-AS1 suppressed the malignant progression of thyroid cancer via the FUS/Numbl axis." (PMID 35599603, 2022).
clear cell sarcoma (4 papers, 2021 to 2024). A rare malignant neoplasm with melanocytic differentiation characterized by the presence of polygonal or spindle shaped clear cells. "Although EWSR1::ATF1 and FUS::ATF1 fusions are reported in clear-cell sarcomas and AFH,25,26 the cases herein with EWSR1/FUS::ATF1 fusions were very close to the AFH cluster, but clearly separated on the UMAP projection." (PMID 39059063, 2024).
hepatocellular carcinoma (4 papers, 2020 to 2025). A malignant tumor that arises from hepatocytes. "Even though the mechanism by which FUS affects the development of hepatocellular carcinoma is unknown, the data suggest that FUS might play a role in the pathology by interacting with the identified lncRNAs." (PMID 38473229, 2024). "LncRNA SchLAH inhibits hepatocellular carcinoma metastasis via interacting with FUS." (PMID 32549791, 2020).
lung carcinoma (4 papers, 2010 to 2023). "Recently, long intergenic non-protein coding RNA 205 (Linc00205) have been found to promote malignancy in lung cancer by recruiting the RNA-binding protein FUS to stabilize CSDE1 mRNA, which enhances lung cancer cell proliferation, apoptosis, and migration." (PMID 35179516, 2022). "Some newly uncovered aberrations contained oncogenes such as FUS at 16p11.2 and NSD1 at 5q35.2–q35.3, whose association with lung cancer has hitherto not been reported." (PMID 21151896, 2010).
pancreatic cancer (4 papers, 2015 to 2024). "In conclusion, exosomal HSPB1 interacts with the RNA binding protein FUS and decreases FUS‐mediated stability of Nrf2 mRNA, thus suppressing hypoxia‐induced ferroptosis in pancreatic cancer." (PMID 38682349, 2024). "We also explored the specific regulatory mechanism of SOX2OT and its downstream protein FUS in pancreatic cancer cell migration and invasion." (PMID 34552054, 2021). "In conclusion, we screened HSPB1 as an exosomal protein regulator for ferroptosis of pancreatic cancer cells, and exosomal HSPB1 played a promoting role in pancreatic cancer progression by interacting with the RNA binding protein FUS and suppressing FUS/NRF2/HO‐1/P450‐mediated ferroptosis." (PMID 38682349, 2024). "SOX2OT regulates the levels of a large number of mRNAs through modulating FUS in pancreatic cancer." (PMID 34552054, 2021). "RBPs binding represents a major mechanism where lncRNAs exert their roles through several cancer-related pathways, while RBPs show diverse effects on gene expression-related processes; for instance, lncRNA SOX2OT combines with FUS by promoting pancreatic cancer proliferation." (PMID 34746238, 2021). "However, FUS had negative regulatory effects on the tumor growth and metastasis of pancreatic cancer cells and FUS overexpression could obviously reverse the carcinogenesis caused by SOX2OT." (PMID 34552054, 2021). "In conclusion, SOX2OT may bind to FUS protein to promote its degradation via ubiquitination, thereby promoting cell proliferation, migration, and invasion, then affecting the development of pancreatic cancer." (PMID 34552054, 2021). "It is revealing that the depletion of RBMX, EWS, FUS, SKIP and Tra2 all augment DNA damage-induced apoptosis, and that knocking down PTBP1 abolishes resistance to genotoxic drugs in pancreatic cancer cells." (PMID 26529031, 2015). "In this study, we demonstrated that FUS bound to and stabilized the mRNA of the ferroptosis suppressor gene NRF2 and regulated NRF2‐mediated suppression of ferroptosis, thus contributing to pancreatic cancer cell proliferation and invasion." (PMID 38682349, 2024). "To determine whether the regulation of FUS protein by SOX2OT affects the migration and invasion of pancreatic cancer cells, we reversed the regulation of FUS protein by SOX2OT using ectopic expression of FUS." (PMID 34552054, 2021). "However, the mechanism of SOX2OT binding and inhibiting FUS protein stability remains unclear, and the role of SOX2OT–FUS regulatory axis in pancreatic cancer cell migration and invasion is still unclear." (PMID 34552054, 2021).
prion disease (4 papers, 2020 to 2025). A transmissible disease that is caused by a protein that is able to induce abnormal folding of normal cellular proteins, leading to characteristic spongiform brain changes, which are associated with neuronal loss without an inflammatory response. "In addition, the coexistence of prion disease and FTD in patients suggests an association between the PrPSc deposits in prion disease and the hyperphosphorylated tau, TDP-43, or FUS aggregates in FTD." (PMID 35768878, 2022).
rhabdomyosarcoma (4 papers, 2022 to 2025). A rare aggressive malignant mesenchymal neoplasm arising from skeletal muscle. "The translocation of TFCP2 (usually exon 2) with either FET family member—EWSR1 (usually exon 5) or FUS (usually exon 6)—most often results in an epithelioid variant of rhabdomyosarcoma." (PMID 40361368, 2025). "Background/Objectives: The fusion of the TFCP2 gene with either EWSR1 or FUS typically results in a spindle cell and/or epithelioid variant of rhabdomyosarcoma." (PMID 40361368, 2025). "Rhabdomyosarcoma with TFCP2 rearrangement (TFCP2-RMS) is a high-grade rhabdomyosarcoma, characterized by a fusion of TFCP2 to EWSR-1 or FUS." (PMID 35059992, 2022). "We leverage two precision oncology programs to investigate rhabdomyosarcoma with FUS/EWSR1-TFCP2 fusions, an orphan malignancy without effective therapies." (PMID 38168093, 2024).
semantic dementia (4 papers, 2012 to 2025). "The top 10 clusters that reflect the knowledge base and research progress in FTD are #0 semantic dementia, #1 FTDP-17, #2 TDP-43, #3 C9orF72, #4 progranulin, #5 protein aggregation, #6 biomarkers, #7 FUS, #8 primary progressive aphasia, and #9 psychosis." (PMID 39087008, 2024).
soft tissue sarcoma (4 papers, 2019 to 2025). A malignant neoplasm arising from muscle tissue, adipose tissue, blood vessels, fibrous tissue, or other supportive tissues excluding the bones. "We hypothesize that this distinctive morphology and molecular phenotype may be linked to the high-grade transformation (HGT) process of low-grade malignant soft tissue sarcoma, where tumor development is driven by the FUS:: CREB3L2 fusion, leading to dedifferentiation into a pure SEF form." (PMID 40144208, 2025).
acute lymphoblastic leukemia (3 papers, 2013 to 2022). Leukemia with an acute onset, characterized by the presence of lymphoblasts in the bone marrow and the peripheral blood. "TLS/FUS-ERG is mainly reported in AML, but not in myelodysplastic syndrome (MDS) evolved to AML, acute lymphoblastic leukemia (ALL), blast crisis of chronic myelogenous leukemia (CML), and Ewing’s tumors." (PMID 36181538, 2022).
amyloid (3 papers, 2019 to 2024). "This review aims to synthesize and consolidate the biophysical knowledge of the sequences, structures, stability, dynamics, and inter-domain interactions of FUS and TDP-43 domains, so as to shed light on the molecular mechanisms underlying their liquid-liquid phase separation (LLPS) and amyloidosis." (PMID 38029395, 2024). "Staining for fused-in-sarcoma (FUS) and TAR DNA-binding protein 43 (TDP-43) proteins was negative, and no amyloid plaques were observed; tau pathology was scarce." (PMID 30935398, 2019).
Chorea (3 papers, 2016 to 2022). Chorea (Greek for 'dance') refers to widespread arrhythmic involuntary movements of a forcible, jerky and restless fashion. "The FUS, VCP, and SETX genes have low mutation frequencies in ALS with chorea; however, the more subtle features of ALS with chorea due to mutations in these genes need to be further explored." (PMID 36596053, 2022). "ALS with chorea can be caused by abnormal amplification of a CAG sequence in the HTT gene and FUS, VCP, and SETX mutations." (PMID 36596053, 2022). "The FUS, VCP, and SETX genes also have low mutation frequencies in patients with ALS and chorea." (PMID 36596053, 2022). "In the present study, we identified a new FUS fragment of approximately 33 kDa in the insoluble fraction, which was derived from a patient diagnosed as having BIBD with chorea." (PMID 27044537, 2016). "Triton X-100 soluble and insoluble brain fractions extracted from patients diagnosed as BIBD with chorea, aFTLD-U, or NIFID, as well as from a control patient were separated by 7.5 % sodium dodecyl sulfate polyacrylamide gel electrophoresis (SDS-PAGE) and immunoblotted with an anti-FUS antibody." (PMID 27044537, 2016).
colon cancer (3 papers, 2019 to 2023). "For example, high expression of circSPARC in colon cancer contributed to accumulation of pro-phosphorylated (p)-STAT3 and facilitated its nuclear translocation via sponging miR-485-3p and recruitment of FUS." (PMID 35338119, 2022). "RMST, a proliferation and apoptosis-related lncRNA, binds with FUS located in the nucleus and enhances SUMO1 modification at the K333 site of FUS, thereby enhancing the stability of the complex, which promote mitosis and migration of colon cancer cells." (PMID 37777749, 2023).
intellectual disabilities (3 papers, 2015 to 2026). "Certain FUS mutations have been associated with comorbid intellectual disability, suggesting neurodevelopmental involvement." (PMID 42295687, 2026). "An association between FUS mutations and early-life intellectual disabilities (IDs) has been reported, particularly in cases involving variants that disrupt the NLS." (PMID 40659544, 2025). "In patients who suffer from mental retardation, SPG11 may be responsible in UMN-dominant cases and FUS may be responsible in LMN-dominant cases." (PMID 26213621, 2015).
lung adenocarcinoma (3 papers, 2010 to 2021). A carcinoma that arises from the lung and is characterized by the presence of malignant glandular epithelial cells. "Reduced proliferative capacity was observed in multiple FUS−/− U-2 OS clones as well as FUS-deficient NCI-H460 lung adenocarcinoma cells." (PMID 34375640, 2021). "In addition, there are some genes in other modules that can have very important roles in lung adenocarcinoma, namely DLGAP5, BIRC5, PSMD2, Src, TTK, SENP2, PSMD2, DOK2, FUS among others." (PMID 23874428, 2013). "While our data are consistent with FUS as a candidate gene in lung adenocarcinoma in never smokers, they do not prove that FUS is the functional target of the amplification." (PMID 21151896, 2010).
myocardial infarction (3 papers, 2021 to 2024). Gross necrosis of the myocardium, as a result of interruption of the blood supply to the area, as in coronary thrombosis. "In the cardiovascular system, circFndc3b can reduce cardiomyocyte apoptosis and fibrosis and enhance angiogenesis by promoting VEGF expression and signaling via its interaction with the RNA-binding protein fused in sarcoma (FUS) after myocardial infarction (MI)." (PMID 34447414, 2021).
triple-negative breast carcinoma (3 papers, 2022 to 2024). An invasive breast carcinoma which is negative for expression of estrogen receptor (ER), progesterone receptor (PR), and human epidermal growth factor receptor 2 (HER2). "Another report concerning triple-negative breast cancer indicated that FUS could regulate the biogenesis of circHIF1A and that FUS was transcriptionally regulated by NFIB." (PMID 39550559, 2024). "In triple-negative breast cancer, FUS facilitates the cyclization of circTBC1D14 by binding the downstream flanking sequence of circTBC1D14, which promotes the progression and aggressiveness of triple-negative breast cancer in vivo." (PMID 39550559, 2024).
argyrophilic grain disease (2 papers, 2022 to 2023). A tauopathy characterized pathologically by the presence of silver stain positive lesions called argyrophilic grains, oligodendrocytic coiled bodies, and neuronal tau-positive pretangles. "Neuropathological evaluation revealed diffuse argyrophilic grain disease (AGD), atypical TDP-43 pathology and NIFID with FUS-positive inclusions, consistent with mixed FTLD (FTLD-tau, FTLD-TDP and FTLD-FUS)." (PMID 37415197, 2023).
ataxia telangiectasia (2 papers, 2022). Ataxia-telangiectasia is the association of severe combined immunodeficiency (affecting mainly the humoral immune response) with progressive cerebellar ataxia. "Previous studies revealed that phosphoinositide 3-kinase–like kinase family kinases, for example, DNA-PK and ataxia–telangiectasia mutated, phosphorylate the S/T-Q motif in the LC domain of FUS." (PMID 35753345, 2022).
atherosclerosis (2 papers, 2020 to 2024). A disease characterized by the build-up of fatty material and calcium deposition in the arterial wall resulting in partial or complete occlusion of the arterial lumen. "Fused in sarcoma (FUS), an RNA-binding protein, is implicated in alternative splicing related to apoptosis and proliferation in atherosclerosis." (PMID 39742258, 2024).
cognitive decline (2 papers, 2019). "Only one patient carrying a FUS p.K510E mutation exhibited cognitive decline four months after disease onset." (PMID 31788332, 2019).
desmoplastic small round cell tumor (2 papers, 2008 to 2020). Desmoplastic small round cell tumor (DSRCT) is an aggressive soft tissue cancer that typically arises in serous lined surfaces of the abdominal or pelvic peritoneum, and spreads to the omentum, lymph nodes and hematogenously disseminates especially to the liver. "The EWS-WT1 fusion associated with desmoplastic small round cell tumors (DSRCT,) and a truncated protein composed of the first 262 amino acids of FUS with a short tag were used as controls along with FLI-1 and ERG-1 proteins." (PMID 18648544, 2008).
HIV-1 infection (2 papers, 2019 to 2023). The type species of lentivirus and the etiologic agent of acquired immunodeficiency syndrome (AIDS). "For example, mutations in FUS encoding gene can exacerbate the sensibility to HIV-1 infection, and vice versa HIV-1 can increase the cytoplasmic localization of Fused in sarcoma (FUS)." (PMID 36675095, 2023).
lymph node metastasis (2 papers, 2020 to 2023). "A clonal driver mutation in MYCN (MIM: 164840; CRC-190), and subclonal driver mutations in ELF4 (MIM: 300775; 083-03), PTPRB (MIM: 176882; CRC-233 lymph node metastasis), FUS (MIM: 137070), and ERCC4 (MIM: 133520) in CRC-449 were all specific to metastatic tumours." (PMID 33053768, 2020).
malignant mesothelioma (2 papers, 2020 to 2024). A malignant neoplasm of the pleura or peritoneum, arising from mesothelial cells. "Interestingly, malignant mesotheliomas were recently found to be associated with recurrent EWSR1/FUS fusions." (PMID 32664515, 2020). "We found a female predominance, except for cases harboring NR4A3 and SUFU malignant mesothelioma, and most patients were around 60 years at diagnosis, but those harboring ALK or EWSR1/FUS::ATF1 gene fusions were younger." (PMID 39059063, 2024).
mesothelioma (2 papers, 2023 to 2024). A usually malignant and aggressive neoplasm of the mesothelium which is often associated with exposure to asbestos. "The location of our cases 1 and 3 at the serosal surface of the adnexa and the morphological findings reveal certain overlap with mesothelioma in young adults that also occasionally harbors ESWR1/FUS::CREB-related fusions." (PMID 37097347, 2023).
myelodysplastic syndrome (2 papers, 2022 to 2023). A clonal hematopoietic disorder characterized by dysplasia and ineffective hematopoiesis in one or more of the hematopoietic cell lines. "FUS-ERG is a chimeric gene with a poor prognosis, found in myelodysplastic syndromes (MDS) and acute myeloid leukaemia (AML)." (PMID 37660196, 2023).
osteoporosis (2 papers, 2023 to 2025). A condition of reduced bone mass, with decreased cortical thickness and a decrease in the number and size of the trabeculae of cancellous bone (but normal chemical composition), resulting in increased fracture incidence. "The regulatory effects of the core genes of the ALS pathway (SOD1, FUS, TARDBP) on ROS metabolism and inflammatory responses are common pathological drivers of Osteoporosis and stroke." (PMID 41379792, 2025).
ovarian carcinoma (2 papers, 2024 to 2026). A malignant neoplasm originating from the surface ovarian epithelium. "However, both KAT6AIDR‐FUS, whose LLPS was rescued by IDR from FUS, and KAT6AC543G/G657E enhanced PARPi resistance in ovarian cancer cells, indicating that KAT6A LLPS, but not its catalytic function, counteracted the effects of PARPi." (PMID 38973255, 2024).
schizophrenia (2 papers, 2020). A major psychotic disorder characterized by abnormalities in the perception or expression of reality. "Fused in Sarcoma (FUS) has been shown to act as a negative repressor of at-RA signalling via the RAR:RXR heterodimer during haematopoiesis and had significantly increased expression in schizophrenia samples." (PMID 31666680, 2020).
schwannoma (2 papers, 2024 to 2025). A benign, usually encapsulated slow growing tumor composed of Schwann cells. "We present a case of a 51-year-old male with a pseudoglandular cellular schwannoma arising from the brachial plexus, which contains the expected molecular aberrations for a schwannoma (chromosome 22q loss encompassing the NF2 and LZTR1 genes) as well as a FUS::KLF17 rearrangement." (PMID 40878925, 2025). "While the spectrum of tumors with fusions involving FUS and EWSR is relatively broad, no cases, to our knowledge, have been reported of schwannomas, let alone the morphologically distinct pseudoglandular schwannoma, containing a FUS rearrangement." (PMID 40878925, 2025).